GAS6 (growth arrest specific 6)
Diseases named in the same sentence as GAS6 in open-access papers (continued):
Sharing a sentence is not in itself a finding about the gene and the disease.
tumor (continued). "Additionally, GAS6 was widely expressed in myeloid cells, fibroblasts, endothelial cells, thyroid epithelium, and tumor cells." (PMID 40433916, 2025). "In addition, blocking the AXL ligand Gas6 signalling also makes NK cells work harder, which shows how important this pathway is in mouse tumours." (PMID 40088262, 2025). "We found that WNT-activated malignant epithelial cells interacted intensively with immune-regulatory tumor-associated macrophages (Reg-TAMs) via the growth arrest–specific 6/AXL receptor tyrosine kinase/MER proto-oncogene, tyrosine kinase (GAS6/AXL/MERTK) pathway." (PMID 39774471, 2025). "In addition, GAS6 also modulates the immunological microenvironment of the tumour, regulates the secretion of cytokines and the functions of various immune cells, and thus triggers an immunosuppressive microenvironment of the tumour." (PMID 40943271, 2025). "Soluble Axl (sAxl), generated through proteolytic cleavage of the extracellular domain, acts as a decoy receptor and may modulate Gas6 bioavailability in the tumor microenvironment, thereby influencing Axl activity." (PMID 41011010, 2025). "GAS6 was the only well‐characterized Gla protein that regulated oncogenic signalling pathways through binding to and activating Axl receptor tyrosine kinase on tumour cells, which was overexpressed in several types of cancer." (PMID 39843398, 2025). "We found intensive reciprocal interactions between TICs and immune-regulatory tumor-associated macrophages (Reg-TAMs) via growth arrest–specific 6/AXL receptor tyrosine kinase/MER proto-oncogene, tyrosine kinase (GAS6/AXL/MERTK) signaling pathways, which facilitated the immune escape of TICs." (PMID 39774471, 2025). "Functional assays, including scratch wound healing, invasion, and migration experiments, further demonstrated that GAS6 + macrophage co-culture and GAS6 treatment significantly enhanced tumor cell motility and invasiveness, while BMS-777,607 treatment abolished these effects." (PMID 41034991, 2025). "Furthermore, co-culture of OSCC cells with THP-1 cells enhances the expression of Axl and its ligand, Gas6, and NF-κB transcription activity in cancer cells that, in turn, acquire tumor invasion/migration abilities and express EMT related genes." (PMID 38397187, 2024). "Gas6 overexpression promotes the migration and invasion of a variety of tumor cells." (PMID 39451556, 2024). "Gas6 produced by tumor and ependymal cells was predicted to interact with the receptor Mertk in myeloid cells, Tyro3 in tumor cells and Axl in ependymal cells, while additional App-Cd74 signaling axes were predicted between tumor, myeloid, endothelial and ependymal cells." (PMID 38566128, 2024). "Importantly, perivascular cell-derived EVs contain GAS6, which activates the GAS6/Axl pathway in endothelial cells to promote tumor angiogenesis." (PMID 39256347, 2024). "At the same time, they may also promote tumor progression through interactions with fibroblasts, endothelial cells, and monocytes via GAS6-AXL and ANXA1-FPR1 signaling." (PMID 39776914, 2024). "Therefore, activation of the HGF-MET and GAS6-AXL pathways promotes tumor survival, proliferation, infiltration, and metastasis, and blocking VEGF can lead to MET and AXL activation." (PMID 38289361, 2024). "The measurement of Gas6 expression may serve as a potential indicator for the diagnosis and prediction of relevant tumor progression." (PMID 39451556, 2024). "Consequently, recombinant protein dimers comprising of the entirety or part of TAM RTK extracellular domain fused with human IgG-derived Fc domain that can inhibit GAS6-dependent tumor cell survival have been developed." (PMID 39062902, 2024). "Moreover, metastatic PC cells infiltrated by neutrophils express Gas6 which activates AXL receptor on tumor cells to facilitate their growth." (PMID 38581008, 2024).
tumor (continued). "To mimic and verify whether ligand–induced activated AXL interacts with MIG6 in a tumor microenvironment, we applied GAS6, a ligand for the AXL receptor, to activate AXL in vitro." (PMID 37834326, 2023). "Interestingly, Axl/Gas6 signaling can also regulate tumorigenesis to support tumor cell survival, migration, and angiogenesis." (PMID 38127424, 2023). "Overall, these data further strengthen the notion that GAS6-CAR-T cells may be an effective therapy targeting both tumor cells and tumor-associated macrophages." (PMID 37475048, 2023). "Upregulation of Gas6/AXL is associated with carcinogenesis in multiple malignancies and shortens overall survival, and may be involved in tumor cell proliferation, migration, apoptosis, and maintenance of tumor stem cells through multiple signaling pathways." (PMID 37265798, 2023). "GAS6/AXL was involved in promoting tumour cells’ proliferation, survival, and angiogenesis." (PMID 36813833, 2023). "GAS6–AXL is also an important signaling axis in tumor neovascularization." (PMID 36816799, 2023). "Compared to Mock T cells, GAS6-CAR-T cells presented with significantly reduced tumor growth." (PMID 37475048, 2023). "Similarly, TAM receptors (Tyro3, Axl, and MerTK), the cognate receptors of GAS6 on apoptotic cells, are also expressed on TAMs and skew polarization toward a pro-tumor M2-like phenotype, participating in immune homeostasis and tumor progression." (PMID 38274812, 2023). "The intervention of the MerTK-PROS1/GAS6-PtdSer axis may be a potent candidate for developing anti-tumor therapy." (PMID 36497444, 2022). "In this context, our data suggest that the modulation of MICA on tumor cells may be a potential limiting effect of GAS6/TAM inhibitors on immune surveillance." (PMID 35967396, 2022). "The over-expression and signaling of the receptor tyrosine kinase AXL by its ligand Gas6 on the surface of several cancer cell lines has been shown to promote their tumor progression, to correlate with their metastatic potential, and can lead to resistance to current cancer therapy." (PMID 36551940, 2022). "Indeed, KRAS mutated tumor cells induced stromal cells to secrete IGF1 and GAS6 that in turn activated IGF1R and AXL signaling in tumor cells, leading to increased mitochondrial performance, proliferative capacity, and resistance to apoptotic stimuli." (PMID 36324182, 2022). "The relevance of Gas6 in prognosis of chRCC tumor patients needs further investigation." (PMID 35760058, 2022). "However, as Gas6 showed a high potential as prognostic and therapeutic marker in several tumor entities." (PMID 35760058, 2022). "Therefore, Gas6 plays a dominant role in connecting tumour dormancy and bone microenvironment with the inflammation network." (PMID 36307871, 2022). "Tumor specimens were analyzed for Gas6 expression by immunohistochemistry." (PMID 35760058, 2022). "AXL could bind to GAS6 and activate multiple pathways and participate in multiple processes of tumorigenesis, including regulating tumor cell growth, proliferation, migration, invasion and enhancement angiogenesis, etc." (PMID 35782741, 2022). "However, this is a complex field and other tumours can be inhibited by an increased Gas6 and TAM expression." (PMID 34836355, 2021). "Therefore, this review focuses on the role of the GAS6/AXL signaling pathway in triggering the immunosuppressive tumor microenvironment as immune evasion." (PMID 34778071, 2021). "Therefore, targeting the Gas6/Axl pathway offers an attractive and promising approach to impair tumor progression and dissemination." (PMID 34576116, 2021). "The engagement of PtdSer with GAS6 may lead to the activation of AXL signaling in hybrid EMT/MET tumour cells." (PMID 34638349, 2021). "Similarly, in a triple-negative breast cancer model, 20G7-D9 decreased tumor growth in vivo and silenced the Gas6-induced upregulation of EMT markers, including Snail, Slug, Twist, and Zeb1/2." (PMID 34576116, 2021).
tumor (continued). "AXL is overexpressed in cells of solid tumours suggesting that GAS6-AXL-DOCK180-ELMO pathway may theoretically enable cancer cells to clear tumour tissues from apoptotic corpses." (PMID 34638349, 2021). "Moreover, GAS6 functions in a wide variety of cancers, and analysis of the tumor microenvironment suggests that GAS6 is a therapeutic target." (PMID 34310342, 2021). "In addition, studies demonstrate that the Gas6/Axl signaling pathway also modulates the tumor microenvironment." (PMID 34576116, 2021). "Once tumor cells colonize the bone, tumor cells may further induce Gas6 expression and secretion by bone marrow derived macrophages (BMDMs) to further promote tumor growth and bone remodeling." (PMID 33791875, 2021). "This study suggests that targeting of the Axl-TGF-β-Gas6 axis may be an effective strategy for inducing dormancy in tumor cells." (PMID 33805598, 2021). "However, Gas6 has been shown to increase formation of bone resorption pits and promote proliferation of tumor cells." (PMID 33791875, 2021). "Functionally we found that the downregulation of hMENA/hMENAΔv6 expression in tumor cells inhibits the GAS6‐induced cancer cells invasiveness, indicating that hMENA expression in both tumor cell and CAFs may empowered the paracrine GAS6‐AXL axis." (PMID 32909687, 2020). "Collectively, the contact with extracellular matrix may lead to AXL overexpression in cancer cells and Gas6, secreted by some stromal cells, could induce the polarization of the Golgi toward the microenvironment allowing the escape of tumor cells." (PMID 31963783, 2020). "It is also possible that low levels of Gas6 may be required to sustain Axl activation in tumor cells." (PMID 32352034, 2020). "Mechanistically, we identified that this hMENA‐mediated pro‐tumor function is attributable to its ability to regulate growth arrest‐specific 6 (GAS6) in CAFs and AXL in tumor cells, sustaining the pro‐tumoral paracrine GAS6‐AXL axis, described as crucial in EMT, drug resistance, and immune evasion." (PMID 32909687, 2020). "AXL could be a powerful actor of the ability of cancer cells to escape the tumor core through its expression in cells at the contact with the stroma and its stimulation by Gas6 secreted in the tumor microenvironment." (PMID 31963783, 2020). "Previous studies have shown that Gas6-Axl signaling promotes tumor cells' EMT." (PMID 32174917, 2020). "However, in vivo, tumour derived Gas 6 responses are enhanced, due to elevated Axl/Gas6-signallling in FAKKO pericytes, and this response results in the enhanced tumour growth in pdgfrβcre+;fakfl/fl mice." (PMID 32499572, 2020). "Notably, leukocytes infiltrating through cancerous tissues upregulate Gas6, which contributes to tumor growth and invasion." (PMID 32370748, 2020). "Indeed, hMENA expression not only promotes the secretion of GAS6 in CAFs but also regulates AXL expression and GAS6‐mediated AXL activation in tumor cells." (PMID 32909687, 2020). "Interestingly, multiple adjacent normal female reproductive tissues including breast, uterus, ovary, and cervix expressed higher levels of Gas6 mRNA than their tumor counterparts." (PMID 32352034, 2020). "Gas6 and Pros1 are ubiquitously produced by in vitro derived myeloid cells, suggesting that they could be a source of ligands within the tumor microenvironment." (PMID 33101282, 2020). "Aberrant Gas6/AXL expression has been described in several tumor types, including RCC." (PMID 33072597, 2020). "Finally, a tumor‐bearing nude mouse model was established to verify the relationship between the expression of miR‐34a, Axl and Gas6 mRNA in vivo." (PMID 31777195, 2020). "Hence, both neoplastic and host cells found in the TME utilize the Gas6/Axl signaling pathway to promote aggressive tumor phenotypes." (PMID 32660000, 2020). "Factors secreted within the tumor microenvironment are able to sustain Gas6/Axl signaling." (PMID 32174917, 2020). "A role for GAS6 has also been observed in modulating the tumor microenvironment." (PMID 32148495, 2020).
tumor (continued). "Hence, the interactions between the neoplastic and host immune cells in the tumor microenvironment can potentiate the expression of Axl and Gas6 to promote a pro-tumorigenic microenvironment." (PMID 32660000, 2020). "Further, we asked whether the effect of hMENA/hMENAΔv6 in CAF‐driven tumor cell invasion relies on the ability of hMENA to regulate GAS6 secretion." (PMID 32909687, 2020). "As expected, control treated mice showed high levels of Axl receptor activation in tumors, whereas the anti-Gas6 treated group showed markedly reduced levels of Axl receptor activation, confirming that anti-Gas6 antibody has reached the tumor and has blocked Axl signaling." (PMID 32174917, 2020). "Many studies have shown that Gas6/AXL plays a big role in promoting tumor metastasis." (PMID 31110076, 2019). "However, in the same tumor sample with overexpression of GAS6 (as a ligand), the expression of AXL (as a receptor) in stage I, II was lower than its expression in stages III, IV (high stages)." (PMID 31700829, 2019). "Although, under hypoxic condition, like tumors, hypoxia inhibits down-regulation of AXL by GAS6, consequently, tumor progression toward EMT may occur in cancers." (PMID 31700829, 2019). "The Gas6/Axl (both in transmembrane and soluble forms) system has been, for instance, claimed to be connected to the promotion of tumor invasion in various solid malignancies, as recently confirmed in a meta-analysis conducted on 3,344 total patients (379 with HCC) from 25 studies." (PMID 31583026, 2019). "GAS6 was more strongly expressed in MIBCs than in NMIBCs, suggesting that GAS6 might increase the autocrine or paracrine activation of TYRO3 in muscle-invasive tumours." (PMID 30765874, 2019). "Tumor-infiltrating macrophages secrete GAS6 which supports tumor progression." (PMID 31775787, 2019). "Studies have shown that Gas6/Axl is highly expressed in various tumor tissues and cells." (PMID 31110076, 2019). "Plasma concentrations of AXL and GAS6 do not reflect tumor expression levels, and their measurement is thus not a viable alternative to direct analysis of tumor tissue in EGFR‐mutated NSCLC." (PMID 31419057, 2019). "Stress state in the tumor environment has a crucial role in the induction of GAS6/AXL signaling." (PMID 31700829, 2019). "Similar observations have been made with locally sourced Gas6 as a TAM stimulator on tumour cells." (PMID 31766614, 2019). "In the present study, we measured the plasma concentrations of AXL and its ligand GAS6 to examine whether they might reflect the corresponding expression levels in tumor tissue." (PMID 31419057, 2019). "In addition, by contrast, some studies have shown inhibitory effects of Gas6/ProS1 on tumour growth through inhibition of angiogenesis." (PMID 31766614, 2019). "When tumor cells are cultured with GAS6-null osteoblasts the conversion to CSCs is significantly diminished, and in mice models CSCs are found in much higher numbers in endothelial bone surfaces expressing GAS6." (PMID 30180883, 2018). "We demonstrated that hMENA/hMENAΔv6 identify a subset of CAFs with pro-tumoral functions and defined a novel function of hMENA in regulating tumour/stroma cross-talk via paracrine Gas6-Axl signaling, described as crucial in EMT, drug resistance and immune evasion." (PMID 30400822, 2018). "In HCC, the Gas6/Axl pathway has been identified to promote tumor invasion by activating Slug." (PMID 30567378, 2018). "Additionally, malignant cells fuel tumour growth by stimulating infiltrating leukocytes to produce the mitogen Gas6." (PMID 29386018, 2018). "Thus, crosstalk between tumours and macrophages leads to specific upregulation of Gas6, which promotes tumour progression." (PMID 29386018, 2018). "Therefore we were interested on the combination of this method with targeted human protein biomarkers for tumor vascularization, sAxl and Gas6." (PMID 29876303, 2018).
tumor (continued). "In addition, tumor growth was significantly inhibited in Gas6−/− mice, demonstrating a pro-tumorigenic role for GAS6 in the tumor microenvironment." (PMID 30501104, 2018). "A “decoy receptor” was designed to inhibit Gas6/Axl signalling, which may have the potential to inhibit tumour development in vivo." (PMID 29386018, 2018). "Moreover, immunosuppressive effects of Gas6/TAM in tumour microenvironments also make inhibition of Gas6/TAM effective in treating cancer." (PMID 29386018, 2018). "Intriguingly, Gas6 also has functions in the tumour microenvironment." (PMID 29386018, 2018). "In HCC, there is not only a positive correlation of serum Gas6 and sAxl levels with increased tumor staging, but there might be even an excess of Gas6 levels compared to sAxl." (PMID 30567378, 2018). "Although Gas6 staining was cytosolic and primarily found in carcinoma cells, some samples also displayed stromal positivity, suggesting that the ligand can also be provided by the tumour microenvironment." (PMID 28333143, 2017). "Having established that apoptotic and calcium-mediated stressed cells, via externalized PS, could act as cell-based ligands to activate TAMs in the presence of Gas6/Pros1, we next explored whether PS-positive tumor exosomes could also activate TAMs." (PMID 29176978, 2017). "In addition, we found that different forms of PS-positive cells and tumor exosomes (comprising important sources of PS in the tumor microenvironment) all recruited Gas6 to their surfaces and acted as cell-based or exosome-based ligands to activate TAMs." (PMID 29176978, 2017). "Therefore, we show that tumor cells characterized by inherent high GAS6 expression bear the prerequisite for the switch to the PDK‐RSK‐mTOR pathway." (PMID 28675785, 2017). "Both autocrine and paracrine loops between AXL and its ligands GAS6 promote motility and proliferation of endothelial cells, modulate integrin function to facilitate migration and survival of endothelial and tumor cells, and facilitate cell motility via regulation of RAC and AKT pathways." (PMID 28251492, 2017). "Finally, the pro-inflammatory cytokine Gas6 was induced, which has been shown to promote tumor cell survival and invasion." (PMID 28881599, 2017). "All tumors expressing tumor Axl also expressed stromal Gas6 (p = 0.02)." (PMID 28878389, 2017). "Interestingly, Gas6 also has a role in establishing tumour dormancy in the bone marrow microenvironment and in suppressing intestinal tumorigenesis." (PMID 28333143, 2017). "Both of the enzymes required for γ-carboxylation, namely GGCX and VCOR1, appear to be broadly expressed in cells, including a variety of cells that express Gas6 and contribute to the tumor microenvironment, such as monocytic cells (macrophages) and cancer cells themselves." (PMID 29176978, 2017). "Next, we analyzed the relationship between tumor Axl and stromal Gas6 expression, and prognosis." (PMID 28878389, 2017). "Based on these results, we next hypothesized that Gas6-Axl axis may play a significant role on TGF-β-induced tumor cell growth suppression." (PMID 27819283, 2016). "In a preclinical CRC tumor model it was previously shown that Gas6 is expressed in macrophages." (PMID 27486820, 2016). "Recent studies have indicated that GAS6/AXL signaling has the potential to influence the tumor vasculature, paracrine crosstalk between tumor cells and bone marrow derived stromal cells, tumor-fibroblast interactions, as well as NK cell and macrophage function." (PMID 27834845, 2016). "Similarly, treatment with a Gas6 neutralizing antibody decreased tumor growth in a pancreatic ductal adenocarcinoma model." (PMID 27834816, 2016). "GAS6/AXL signaling promotes tumor progression and metastasis through multiple mechanisms." (PMID 27834845, 2016). "As shown in this study, Gas6 is strongly expressed in macrophages and a macrophage-tumor communication via Gas6 could be acting on Axl." (PMID 27486820, 2016).